CDX2 (caudal type homeobox 2)
Diseases named in the same sentence as CDX2 in open-access papers (continued):
Sharing a sentence is not in itself a finding about the gene and the disease.
tumor (continued). "Of note, CDX2 itself is expressed in tumors as well and does not correlate with tumor cell content reflecting its use as a marker of intestinal origin in case of cancer of unknown primary." (PMID 40410286, 2025). "Thus, there is a heterogeneous expression pattern for these markers within the same patient, and the proportion of CDX2 + and HTR2B + tumor cells may greatly influence patient survival." (PMID 41034989, 2025). "In addition, positive expression of CDX2 and MUC2 in tumor cells was observed only in some areas, indicating that PGA mainly expressed gastric markers, intestinal epithelial differentiation was rare, and only a small amount of gastric-to-intestinal differentiation transition was observed." (PMID 40660594, 2025). "The tumor cells showed patchy positivity for cytokeratin 7 (CK7), strong cytoplasmic staining for alpha-methyl acyl-CoA racemase (AMACR), and were negative for PSA, cytokeratin 20 (CK20), GATA-binding protein 3 (GATA3), tumor protein 63 (p63), and caudal-type homeobox transcription factor 2 (CDX2)." (PMID 40662003, 2025). "For instance, CDX2 expression might identify patients likely to have a more indolent disease course, while absence of such differentiation markers in a tumor might prompt more aggressive management." (PMID 40862793, 2025). "High expression of the CDX2 gene in CRC is linked to a 50% lower death rate compared to cases where it is low or absent, and its proper functioning enhances survival rates without disease progression or tumor recurrence." (PMID 38786321, 2024). "Despite these specific differences, the overall findings from these researchers converge on the conclusion that CDX2-negative tumors frequently exhibit forms of aggressive invasion, consistently emphasizing the marker’s predictive value regarding tumor aggressiveness." (PMID 38786321, 2024). "Similarly, a significant difference in the 5-year DFS was found in a validation cohort of 121 CRC-II patients when corresponding formalin-fixed paraffin-embedded (FFPE) tissues were tested using IHC with 15 CDX2-negative tumour patients." (PMID 39516345, 2024). "However, since grade-3 tumours comprised 9.4% (N = 30) of the total sample, grade-3 CDX2-negative tumours corresponded to six samples of our cohort." (PMID 38439814, 2024). "None of the other tumor tissues stained positive for the intestinal marker CDX2." (PMID 37082125, 2023). "Furthermore, the low-grade tumor in the fallopian tube was negative for CDX2 and TTF1, which led us to believe that it was a primary NET." (PMID 36178284, 2023). "The lack of CDX2 expression in tumor buds may indicate that they are in a state of EMT; thus, it could predict poor prognosis in patients with CRC." (PMID 36186777, 2022). "We hypothesized that CDX2 had a significant relationship with tumor size, the depth grading of tumor invasion, and the presence or absence of lymph nodes." (PMID 36277982, 2022). "Specific tumour cell surface proteins (e.g. HLA-G, PD-L1, CDX2) either alone or in combination with the relative presence of immune cells (CD3 and CD8 positive T-cells) in the tumour tissue may describe the cancer cells’ ability to escape eradication by the immune system." (PMID 35027037, 2022). "In addition, CDX2 expression was not significantly correlated with patient gender, tumor grade, nodal status, and tumor stage." (PMID 35463729, 2022). "No staining for the differentiation marker CDX2 was detected in either non-tumour or tumour tissue." (PMID 33906633, 2021). "Moreover, ectopic expression of PTEN attenuated tumour cell invasion as well as Akt and GSK-3β phosphorylation and EMT marker proteins enhanced by CDX2 knockdown, while knockdown of PTEN antagonised the tumour-suppressive effect of CDX2 overexpression." (PMID 33239678, 2021).
tumor (continued). "Furthermore, LIN28B overexpression resulted in enhanced CDX2 expression to promote differentiation in subcutaneous xenograft tumors generated from CRC cells and metastatic tumor colonization through mesenchymal-epithelial transition in CRC liver metastasis mouse models." (PMID 33755595, 2021). "Notably, CDX2 is not able to identify any additional subset of patients with a poor prognosis, that is not identified by either tumour budding, WHO grade or CRC subtypes." (PMID 34616012, 2021). "Interestingly, CDX2 expression was also increased in the contralateral epithelium, while there was no tumor." (PMID 34563241, 2021). "It is unclear whether the enriched binding sites for FOXA1, HOXB13 and CDX2 are dependent or independent of AR activity in single cells from high-grade tumours." (PMID 34911933, 2021). "Thus, unlike its tumor suppressor activity at its physiological site of expression, the gut, the CDX2 homeobox gene is oncogenic in the ectopic setting of the hematopoietic lineage." (PMID 33960108, 2021). "In addition, overall RNA levels of Notch1, CDX2 and miR-181a were increased in tumor samples relative to non-cancerous tissues (median FC = 2.742, 3.47 and 1.5, respectively)." (PMID 32704077, 2020). "A question remains: why, in this case, was the tumor negative for p63/p40 and positive for CDX2?" (PMID 30890174, 2019). "In this case, the tumor was negative for p63/p40 and positive for CDX2." (PMID 30890174, 2019). "The tumor cells were positive for cytokeratin (CK) 7 and thyroid transcription factor-1, and negative for CK20, special AT-rich sequence-binding protein 2, and caudal type homeobox 2, together indicating that the tumor was a metastatic lesion originating from the lung adenocarcinoma." (PMID 31650415, 2019). "Interestingly, when stratifying the cohort by TSR, no prognostic difference was observed related to CDX2 expression in stroma-low tumours." (PMID 30847807, 2019). "Thirty-nine patients (5.0%) showed a complete absence of CDX2 protein in the tumor." (PMID 30257705, 2018). "In the same manner as the CDX2 investigation, we set a cutoff point of 50% tumor cells to assess whether a tumor is positive or negative for CDX1 protein expression." (PMID 29682204, 2018). "However, in this study, on an examination of cross-sections, primary CRC revealed heterogenous CDX2 expression, and 21.9% (30/137) of CDX2-positive primary CRCs also had CDX2-negative cancer cells in the tumor." (PMID 29682204, 2018). "In the same manner as the CDX2 investigation, we used a whole-section of all the samples and set a cutoff point of 50% of tumor cells to assess whether a tumor is positive or negative for the protein expression." (PMID 29682204, 2018). "Immunohistochemical analyses revealed a similar expression and distribution patterns of CDX2 (nuclear), CK20 (cytoplasmic), E‐Cadherin (membrane), MUC2 (extracellular,; intracellular signet ring PMP) and MUC5AC (extra‐ and intracellular, and Z') in PMP PDX tumor as in human tumors." (PMID 26833741, 2016). "However, our results show that patients without this risk factor, and thus not treated, present a strikingly worse outcome when the tumor presents with a SOX2+/CDX2- molecular profile." (PMID 25300947, 2014). "However, if receptor EphA2 activation with ephrin-A1 induced expression of cdx-2 plays any role in NSCLC tumor growth is not known." (PMID 22824143, 2012). "Moreover, although there was not a significant correlation between Cdx2 expression and tumor size, we detected a trend for smaller tumor size (<5 cm) to be associated with Cdx2-positive." (PMID 23181722, 2012). "In addition, when the A549 cells were transfected with cdx-2 siRNA and subsequently treated with the ephrin-A1 or transfected with pcDNA-EFNA1 we noticed significantly increased tumor formation as compared to cells either activated with ephrin-A1 alone and pcDNA-EFNA1 transfected cells." (PMID 22824143, 2012).
tumor (continued). "Moreover, CDX2 is a more specific marker than CK, CK8, CK18, CK19 and BerEP4 because the former antigen is expressed mainly in tumour and normal cells from the GI tract, whereas the latter antigens are expressed in virtually all carcinomas and all non-neoplastic epithelial cells." (PMID 21364588, 2011). "However, when CDX2 staining is lacking in tumor cells, one can exclude an enteric primary site." (PMID 40430111, 2025). "Thus, CDX2 might induce the migration and infiltration of NK cells, increases the secretion of IFN-γ and TNF-α by NK cells, enhances NK cell toxicity against cancer cells, and suppresses tumour growth." (PMID 36928082, 2023). "However, it remains unclear whether SATB2 is differently expressed within purely morphological (adenocarcinoma NOS vs. specific CRC subtypes, tumour budding subcategories (Bd1/2/3), WHO low- vs. high-grade carcinomas), immunohistochemical (CDX2 expression) and pTNM/UICC stage subgroups." (PMID 34944797, 2021). "Moreover, even in terms of the incidence of liver metastasis, which is an indicator of tumor aggressiveness, we did not perceive a statistically significant difference between the CDX2-low and CDX2-high CRCs (average number of metastasis; 4.9 versus 4.5, P = 0.68)." (PMID 30326864, 2018). "Additionally, in-depth molecular-level investigations have demonstrated that CDX2 can reduce the expression of downstream target genes, including axis inhibition protein 2 (AXIN2) and lung lineage transcription factor Nkx2-1, which subsequently inhibit tumour invasion and metastasis." (PMID 29179508, 2017). "Immunohistochemical (IHC) analysis revealed that the resected gastric specimens showed tumor cells that were positive for both cytokeratin 20 (CK20) and caudal-type homeobox gene 2 (CDX2) and negative for CK7." (PMID 41982867, 2026). "The tumor cells exhibited positivity for CK7 (partial), CK20, CDX2, and CAM5.2, while being negative for GCDFP15, S100, SOX10, GATA3, PAX8, and CK5/6." (PMID 40438862, 2025). "The expression of CDX2 and SATB2 was detected in variable proportions of tumor cell nuclei, while stromal cells were negative for both." (PMID 39998677, 2025). "The tumor cells showed strong nuclear expression for GATA3 but no staining for TTF-1, CDX2, and PAX8, inferring primary breast origin." (PMID 40909459, 2025). "Synaptophysin, chromogranin A, and CD56 are commonly used markers to identify NE differentiation and the non-NE markers include caudal-type homeobox 2 (CDX2), cytokeratin 7 (CK7), CK20, among others depending on the specific neoplasm." (PMID 41041158, 2025). "On immunohistochemical analysis, the tumor was positive for MUC5AC and MUC6 and negative for MUC2 and CDX2, indicating a gastric phenotype." (PMID 41256328, 2025). "The tumor cells were negative for special AT-rich sequence-binding protein 2 (SATB2) and caudal type homeobox 2 (CDX-2), which rules out the possibility that the tumor cells originate from the digestive tract (stomach, small intestine, colon, etc.)." (PMID 40013097, 2025). "Among other immunostains not shown, ATRX nuclear expression was retained in all tumor cells, and none of the tumor cells were positive for IDH1 R132H mutant protein, napsin, NKX3.1, CD45, synaptophysin, INSM1, SOX10 protein, p40, CDX2 protein, PSAP, or PSA." (PMID 38845695, 2024). "Primary tumor cells were diffusely positive for CK7, CK20, Cam5.2 and negative for SOX10, TTF1, PSA, and CDX2." (PMID 38831459, 2024). "The tumor cells were negative expression of CgA, CD56, CK5/6, CK20, Myogenin, MyoD1, Desmin, CEA, S100, CK8/18, CDX2, CD20, CD5, CD3, CD79a, LCA and HMB45." (PMID 38877473, 2024).
tumor (continued). "Immunostaining of the tumour cells was positive for CK7, CK20, and CDX2 but negative for TTF‐1 tumour." (PMID 39324075, 2024). "Immunophenotypically, the tumor was positive for Cytokeratins Oscar and 7, GATA3, GCDFP, HER2, and an androgen receptor but negative for CK20, S100, p40, Melan A, CDX2, TTF1, ER, SATB2, DOG1, synaptophysin, and chromogranin." (PMID 37886914, 2023). "Immunohistochemical staining was carried out and showed positive staining for CK20, CDX2, and SATB2 and negative staining for CK7, indicating the recurrent tumor’s primary colon origin." (PMID 37280577, 2023). "Survival of patients with PB tumours showing CK7/MUC1-positive staining and CDX2-negative staining showed a worse prognosis." (PMID 37504367, 2023). "On immunohistochemical examination, the tumor cells were positive for PSA and P504S, being negative for CDX-2, CK7, CK20, SMA, and LCA." (PMID 37374005, 2023). "The invasive carcinoma, IC, and tumor cells involved in PS expressed PSA and P504S, while CK7, CK20, CDX-2, and GATA-3 were negative." (PMID 37374005, 2023). "Future studies will further investigate this topic by evaluating tumor-infiltrating lymphocytes and CXCL14 expression in the tumor microenvironment, especially comparing CDX-2 positive cases with CDX-2 negative cases." (PMID 36928082, 2023). "In our case, the tumor cells displayed uniform staining for PSA and PSAP, and they were negative for GATA-3, CDX-2, CK7, and CK20." (PMID 37374005, 2023). "Immunohistochemistry staining showed the tumour was positive for AE1/3, CK7, GATA-3 and GCDFP-15; and was negative for CK20, PAX-8, CDX-2, WT-1, TTF-1, mammaglobin and BRAF V600E." (PMID 36871042, 2023). "The tumor cells were immunohistochemically positive using a pan-cytokeratin cocktail (AE1/3) as well as Ber-EP4 and CK7 positive, whereas CK20, CDX2, HMB45, Hepar-1, LCA, and AFP immunostains were negative." (PMID 36761421, 2022). "Core biopsy of left chest wall nodule also revealed poorly differentiated LUAD with tumor cells positive for pan-keratin and TTF-1 and negative for ER, PR, CDX2, WT1, PAX-8, synaptophysin and chromogranin." (PMID 35546239, 2022). "Subsequent immunohistochemistry of the resected anal fistula showed a CDX-2-positive, CK20-positive, CK7-negative, and GCDFP-15 negative tumor, with implantation metastasis." (PMID 35357598, 2022). "The addition of serotonin to CDX2 increases sensitivity to the diagnosis of midgut NET, from 90 to 96%, and should be considered as a second-step marker for those CDX-2 negative tumours." (PMID 35626118, 2022). "Positive staining of CK20, CDX-2, STAB2, and negative staining of CK7 and PAX-8 was observed for the tumor tissue, indicating that the tumor was of gastrointestinal adenocarcinoma origin, rather than ovarian origin." (PMID 35721089, 2022). "Our result showed that the tumor tissue was positive in CK20, CDX-2, STAB2, and negative in CK7 and PAX8, which confirmed the appendix origin." (PMID 35721089, 2022). "Immunohistochemically, the tumor cells were positive for MUC6 and MUC5AC and negative for intestinal-type markers such as MUC2, CD10 and CDX2." (PMID 34160413, 2021). "Immunohistochemical analysis showed tumor cells positive for BMP-2, osteonectin, osteocalcin, AE1/AE3, TGF-β1, Gli2, Smad2/3, and CDX2 and negative for nestin, CD56, and CK7." (PMID 33388078, 2021). "CDX2 and PCAD showed decreased mRNA levels in tumour relative to non-tumour and an absence of these proteins in normal and tumour tissue." (PMID 33906633, 2021). "CDX2-low/absent CRCs were significantly more frequent in higher pT/pN/UICC-stages (P < 0.001, P = 0.039, P < 0.001, respectively) and right-sided tumours (P < 0.001)." (PMID 34616012, 2021).
tumor (continued). "The cell block was tested by IHC and the identified tumor cells were found to be reactive for BEREP4, K7, and CDX2 and negative for TTF1 and calretinin." (PMID 34178989, 2021). "In right-sided CRCs (caecum to splenic flexure), we observed no prognostic impact of CDX2 expression in contrast to a retained high prognostic relevance of CRC subtypes, tumour budding and WHO grade comparable to the data from the overall cohort." (PMID 34616012, 2021). "The tumor cells in all 7 cases expressed IHC stains for PAX8, ER and CK7 and PR and were negative for CK20, CDX2 and WT1." (PMID 33736662, 2021). "Further examinations revealed that nonmucinous tumor cells were positive for CK7 and negative for CK20 and caudal type homeobox 2 (CDX2)." (PMID 33044008, 2020). "The tumor cells with mucinous and signet ring‐like features were positive for CK20 and CDX2 and negative for CK7, indicating enteric differentiation." (PMID 33044008, 2020). "Further examination revealed that tumor cells of the nonmucinous type were positive for CK7, and negative for CK20 and caudal‐type homeobox 2 (CDX2)." (PMID 33044008, 2020). "On the other hand, the tumor cells with mucinous and signet ring‐like features were positive for CK20 and CDX2, and negative for CK7, indicating enteric differentiation." (PMID 33044008, 2020). "Immunostaining revealed that the tumor cells were strongly positive for CK20 and CDX2, whereas the endometrial glands and stroma did not react with CK20 or CDX2." (PMID 32164210, 2020). "Immunohistochemistry demonstrated that the tumor was strongly and diffusely positive for CK7, focally positive for p63 and CDX2, and negative for CK5/6, confirming a gastrointestinal rather than skin origin of the tumor." (PMID 29159772, 2019). "The results of immunostaining for CK5/6 supported that this tumor was SCC, but the question why p63/p40 were negative and CDX2 was positive still remained." (PMID 30890174, 2019). "Immunohistochemistry demonstrated that the tumor cells were diffusely positive for CK7 and negative for CK20 and CDX2." (PMID 31279332, 2019). "Immunohistochemically, both tumor components were negative for CK7, focally positive for CK20, and positive for CDX2 and MUC2." (PMID 31077226, 2019). "Immunohistochemically, both tumor components were negative for CK7, focally positive for CK20, and positive for CDX2." (PMID 31077226, 2019). "Tumor cells were strongly and diffusely positive for CK7, CK19, MUC1 and negative for CK20, CDX‐2, MUC2." (PMID 31102323, 2019). "In both cases, clear and ordinary tumor cells were negative for CK7 and positive for CK20 and CDX2, consistent with findings of colorectal origin." (PMID 31077226, 2019). "In this case, the tumor was positive for CK5/6 and CDX2, slightly positive for CK20, and negative for CK7, p63, and p40." (PMID 30890174, 2019). "Immunohistochemical examination showed that the tumor cells were positive for cytokeratin 7 (CK7) and CDX-2 and negative for CK20." (PMID 29784024, 2018). "The tumor cells in HDGC patients are negative for CDX2, whereas most SDGC cases (with one exception), have shown positive CDX2 expression, implying that HDGC and SDGC have different pathogeneses." (PMID 30568591, 2018). "For example, we found that E-cadherin, ESRP1 staining was greatly increased in tumors from CDX2;APC;PID mice, whereas Msi1 was decreased in these tissues, relative to tumor tissue from animals lacking PID expression." (PMID 30150766, 2018). "At immunohistochemistry, tumor cells were positive for CK20 (cytokeratin 20) and CDX2 (caudal type homeobox transcription factor 2), negative for CK7 (cytokeratin 7) and PSA (prostatic specific antigen)." (PMID 29110729, 2017). "Caudal-related homeobox protein 2 (CDX2), a tumor suppressor in the adult colon, is overexpressed under a non-cancer specific cytomegalovirus promoter in certain tumor cells; furthermore, non-specific expression of CDX2 may result in aberrant side effects in normal cells." (PMID 25847407, 2015).